IL10 (interleukin 10)
Diseases named in the same sentence as IL10 in open-access papers (continued):
Sharing a sentence is not in itself a finding about the gene and the disease.
colitis (continued). "The poor response to IL-10 of the patients’ leukocytes does not appear to be associated with the early-onset colitis seen in patients with AR IL-10, IL-10RA, or IL-10RB deficiencies, possibly because of residual TYK2-independent responses to IL-10." (PMID 36094518, 2022). "Particularly, an anti-inflammatory effect of TGR5 activation by ligands such as BAR 501 through a reduction in IL6, TNFa, and INFy, an increase in IL10, and the promotion of macrophage differentiation from the M1 to the M2 phenotype has been observed in mice models of colitis." (PMID 35807844, 2022). "In addition to Th17 cells, the IL-1β-ERK-RORγtS182 axis is required for maintaining a subset of the RORγt+ Treg populations in the steady-state colon, as well as regulating their anti-inflammatory cytokine IL-10 production capacity during colitis." (PMID 35294872, 2022). "L. acidophilus FAHWH11L56 could significantly increase IL-10 in this study, and this result was consistent with previous research that the other two L. acidophilus strains could also increase IL-10 in colitis mice." (PMID 36499169, 2022). "Furthermore, investigations on the faecal samples from two genetically colitis-prone mice, namely IL10-/- and Winnie-/- mice, both witnessed more abundant A. muciniphila than their wild-type littermates." (PMID 36685588, 2022). "Furthermore, we demonstrated the loss of protective function of MSCs against acute colitis in mice by blocking TGF-βR, accompanied by the induced loss of IL-10+Bregs." (PMID 35371051, 2022). "Since we demonstrated the critical role of IL-10-producing B cells in MSC-mediated alleviation of colitis, we further investigated whether THBS1 contributed to this effect." (PMID 35371051, 2022). "Downregulation was observed in the levels of both Nrf2 and IL-10 in the colitis group." (PMID 36228298, 2022). "Disturbance of intestinal immune regulation is an essential factor in the pathogenesis of IBD, in which proinflammatory cytokines TNF-α, IL-6, IL-1β and anti-inflammatory cytokine IL-10 are the key indicators reflecting the degree of inflammation in the model of colitis." (PMID 36615796, 2022). "Dietary fiber intake in IL10 knockout mice suppresses colitis." (PMID 35546404, 2022). "In contrast, PAMK treatment slightly increased the expression of Tgfb1 and Il10 in colitis mice." (PMID 36341374, 2022). "Oral administration of NK151, NK175, or their (4:1) mix suppressed cGm-induced colitis in mice: they suppressed colonic myeloperoxidase activity, IL-1β and IL-6 expression, and the NF-κB+CD11c+ cell population, while significantly increasing IL-10 expression." (PMID 35631220, 2022). "In addition, IL-10 has been shown to stimulate mucin production and attenuate colitis in mice by preventing misfolding of mucin protein." (PMID 35736372, 2022). "Lipopolysaccharide (LPS) from Akkermansia leads to higher levels of production of proinflammatory factors by colonic myeloid cells in the lamina propria, and this high LPS activity in iL10-/- mice could promote the development of colitis." (PMID 36713373, 2022). "Studies have shown that CD11b ameliorates symptoms of colitis through IL-10 production; therefore, in mice from Group A (DSS + Que), which showed greater values of CD11b expression, there would appear to be better mobilization of the immune system, which would attenuate the symptoms of the disease." (PMID 36676712, 2022). "However, the colitis-relieving effects of B. breve were reduced after IL-10 receptor knockout in mice, emphasizing the role of IL-10 in the anti-inflammatory effects of B. breve." (PMID 36389768, 2022). "The reduced antibody titers in Il10−/− mice might be a consequence of extended administration of piroxicam, a nonsteroidal anti-inflammatory drug (NSAID) that was necessary to induce colitis in our Il10−/− colony." (PMID 36094114, 2022).
colitis (continued). "In our study, the decrease in IL-4+ and IL-10+ cell frequency in colitis mouse IELs was restored by the administration of T. halophilus, demonstrating that inflammation-related cells invading intestinal tissues may be regulated by T. halophilus." (PMID 35741032, 2022). "In the piroxicam-accelerated Il10 colitis model butyrate levels decrease as inflammation develops." (PMID 36434690, 2022). "Similarly, Akkermansia is found to be abundant in mice with high levels of intestinal inflammation, and acts as a pathogen to promote colitis in IL-10−/− mice." (PMID 36468853, 2022). "IL17A inhibits spontaneous colitis in IL10-/- mice via the inducible nitric oxide synthase pathway." (PMID 35546404, 2022). "Furthermore, sulfasalazine and hFm alleviated cGm-induced colitis: they suppressed myeloperoxidase activity, IL-1β and IL-6 expression and increased IL-10 expression." (PMID 35631220, 2022). "Finally, there are several colitis models, such as the IL-10 knockout mouse model with spontaneous colitis, trinitrobenzene sulfonic acid-induced colitis, polyinosinic-polycytidylic acid-induced colitis, and T-cell transfer-induced colitis." (PMID 36009796, 2022). "Although to a lesser extent than in Il10−/− mice, we also observed reduced colitis severity in Lcn2−/− and WT mice that were immunized with CTB-Ent, despite similar weight courses, and only a transient decrease of fecal AIEC levels compared to respective control-immunized mice." (PMID 36094114, 2022). "IL-10 is another MSC-generated immunoregulatory cytokine which contributes to bowel homeostasis, its deficiency aggravates DSS-mediated colitis whereas its supplementation could become an alternative treatment for IBD." (PMID 36012170, 2022). "Interestingly, engineered IL-27-producing L. lactis proved more effective than both the IL-10 producing counterpart and systemic administration of IL-27 in colitis mouse models." (PMID 35082553, 2022). "In the present study, except for the obvious UC symptoms, we observed an increase in pro-inflammatory cytokines (TNF-α, IL-6) and MPO activity as well as a decrease in anti-inflammatory cytokines such as IL-10, which are closely related to the severity of colitis." (PMID 36295859, 2022). "It was found that rats with immature tapeworms demonstrated increased IL-4, IL-13 and IL-10 expression but were not protected against colitis, while mature H. diminuta caused less severe clinical symptoms." (PMID 36558772, 2022). "VDR-IL10 double knockout mice develop even more severe colitis than IL-10 knockout mice." (PMID 36076980, 2022). "However, adoptive transfer of CD8αα+ IELs into SCID mice did prevent CD4+ T-cell-induced colitis in an IL-10-dependent manner; CD8αα+ IELs derived from IL-10 knockout transgenic mice were ineffective for disease prevention." (PMID 35493508, 2022). "In various cytokines related to colitis, IL-10 is a pleiotropic cytokine that could inhibit NF-κB signaling pathways in the process of inflammation to alleviate chronic inflammatory diseases." (PMID 36499169, 2022). "The enrichment of Alistipes, together with anti-inflammatory cytokine IL-10 and regulatory T cells, could attenuate severe colitis in NOD2 knockout mice." (PMID 35736237, 2022). "Interestingly, VDR/IL-10 double knockout (KO) mice develop colitis after 8 weeks as compared with single IL-10- or VDR-knockout animals that remain relatively healthy at that time." (PMID 35057450, 2022). "In addition, overexpression of circGMCL1 ameliorated experimental colitis and improved intestinal barrier function in IL-10 knock-out (IL-10 KO) mice." (PMID 36088391, 2022). "In our study, we used a chronic colitis model of IL-10−/− mice induced by piroxicam." (PMID 35186102, 2022). "In this study, we used piroxicam to induce IL-10−/− mice to produce a chronic colitis model and explored whether JPQCD could regulate the PERK/eIF2α/ATF4/CHOP pathway, thus improving ER stress and preventing UC." (PMID 35186102, 2022).
colitis (continued). "Milk fat increased the incidence of colitis with typical Th1 inflammatory response in genetically susceptible IL10−/− mice but not in wild-type mice." (PMID 36076980, 2022). "Moreover, immune-suppressive functions of Bregs with IL-10 secretion in colitis, EAE, arthritis and Helicobacter infection have been demonstrated." (PMID 33907502, 2021). "In acute colitis, we speculate that L. reuteri promotes IL‐10 and dampens pro‐inflammatory cytokine production, thereby improving colitis." (PMID 33463911, 2021). "In this study, norovirus infection exacerbated colitis only in IL10-deficient mice carrying ASF but not those colonized with OMM12." (PMID 34836426, 2021). "Interestingly, 68% of IL-10−/− animals with H. hepaticus-triggered colitis shed C. difficile in their feces 1 day after challenge." (PMID 34126769, 2021). "IL-4 and IL-10 are anti-inflammatory mediators with plenty of protective effects in colitis." (PMID 34090510, 2021). "Another study showed L. plantarum LS/07 could promote the IL-10 production in rats with colitis; and thus, L. plantarum LS/07 could be applicable in treating inflammation disease." (PMID 33828554, 2021). "This indicates that IL-10 was necessary for ET to alleviate colitis in this model." (PMID 33717186, 2021). "Moreover, the induction of colitis was also followed by a marked decrease in the anti-inflammatory cytokine IL-10 (normal: 9.6 ± 1.7 pg/mL; DNBS: 4.2 ± 0.8 pg/mL)." (PMID 34199160, 2021). "Similarly, TNBS administration also notably (P < 0.001) decreased the IL-10 levels in colitis control group (0.7032 ± 0.05 pg/ml/mg protein) compared to the non-colitis group (1.386 ± 0.16 pg/ml/mg protein)." (PMID 34539597, 2021). "To better understand the lack of an effect of Il33 deficiency on colitis in Il10−/− mice, we examined colon Il33 expression in WT and Il10−/− mice at 12 and 30 weeks of age." (PMID 33953267, 2021). "This connection between FXR and inflammation is made more confusing in DSS and IL10 KO colitis." (PMID 34831429, 2021). "Interestingly, after treatment with L.p R3 or/and MSLZ, the peripheral blood IFN-γ, IL-17A, and IL-17F levels were significantly decreased (p < 0.05), but blood IL-10 levels were significantly increased (p < 0.05) in the DSS-induced colitis mice." (PMID 34407839, 2021). "Results were validated in a spontaneous colitis Il10−/− mouse model." (PMID 34814945, 2021). "But there are also contrary studies pointing out that H. hepaticus does not induce or potentiate colitis in IL-10 deficient Mice." (PMID 33777833, 2021). "Additionally, various F. prausnitzii isolates have abilities to simulate IL-10 secretion by dendritic cells (DCs), which suggests the anti-inflammatory role of F. prausnitzii in colitis." (PMID 32601832, 2021). "We showed that infection of the non-permissive murine host with H. diminuta 8 days prior to intra-rectal DNBS resulted in significantly less colitis, and that systemic administration of neutralizing IL-10 antibodies negated the anti-colitic effect of infection with this helminth." (PMID 34451458, 2021). "A recent study on an IL-10(-/-) transfer model of colitis stated that dietary histidine reduced histologic damage and colon weight, and tumor necrosis factor (TNF)-α mRNA expression and histidine inhibited lipopolysaccharide (LPS)-induced nuclear factor (NF)-κB in macrophages." (PMID 35053004, 2021). "Furthermore, CB prevents acute experimental colitis in mice by inducing the production of interleukin-10 (IL-10), which is an anti-inflammatory cytokine." (PMID 34277756, 2021). "Expression of pro-inflammatory cytokines, including IL-1β, IFN-γ, and TNFα was decreased in colon tissue of EV treated mice compared to DSS-induced colitis mice, whereas expression of the anti-inflammatory cytokines IL-10 and TGFβ were significantly increased in colon tissue of EV treated mice." (PMID 33670708, 2021). "We firstly found that Il1b was induced over 1000-fold more in DSS compared to Il10−/− colitis." (PMID 33953267, 2021).
colitis (continued). "Indeed, transfer of a gut microbiota enriched in these bacterial taxa during acute and chronic experimental colitis is capable to modulate directly both innate and adaptive mucosal immune responses by inducing IL10-dependent anti-inflammatory responses." (PMID 33549144, 2021). "Therefore, L.p R3 strain inhibits the expression of IFN-γ and IL-17A, while promotes the expression of CD25, Foxp3 and IL-10 in murine DSS-induced colitis tissue." (PMID 34407839, 2021). "Comparing cytokine concentrations, significantly higher level of pro-inflammatory cytokines IL-6 and IL-17A and anti-inflammatory cytokine IL-10 were found in DSS-induced colitis group (p < 0.05, p < 0.001 and p < 0.001, respectively) compared to all other groups." (PMID 33540919, 2021). "Furthermore, IL-10 facilities the regulatory T (Treg) cell-mediated suppression of T helper 17 (Th17)-driven colitis in mice." (PMID 34943999, 2021). "Interleukin-10 knockout (IL-10−/−) mice develop spontaneous colitis that is entirely dependent on gut bacteria, and where colonic inflammation is attenuated when treated with antibiotics before disease onset or is eliminated altogether in mice housed in a germ free environment." (PMID 34513862, 2021). "Treg-secreted IL-10 was previously shown to protect mice from spontaneous colitis, and we were concerned that the reduced weight and increased insulin sensitivity in the IL-10fl/fl Foxp3-Cre+ mice were due to colitis." (PMID 33351782, 2021). "Oral delivery of IL-27 recombinant bacteria can ameliorate T cell transfer-induced colitis in mice whilst a T. muris infection in an IL-10/IL-27 KO mouse leads to less severe pathology than seen in the IL-10 KO control due to a decreased pro-inflammatory profile." (PMID 34078488, 2021). "Colonization with enteric Helicobacter species, including Helicobacter hepaticus, has been shown to trigger colitis in genetically predisposed mice, such as those lacking the regulatory cytokine interleukin 10 (IL-10) (16, –, 18)." (PMID 34126769, 2021). "However, to access IL-10 protective effect against colitis, IL-10 signaling pathway must be triggered before the induction of DSS colitis." (PMID 34987390, 2021). "Similarly, Il10−/− mice that develop spontaneous colitis show reduced Nhe3 activity in the enterocyte." (PMID 34546338, 2021). "Moreover, in the case of Lb. curvatus effects on the immune system, one report has shown that Lb. curvatus WiKim38 triggered the activation of dendritic cells and stimulated IL-10 production to suppress chemically-induced colitis in mice." (PMID 34711881, 2021). "Importantly, the concentrations of CCL-2, IL-1β, and IL-6 were significantly downregulated after DSS-induced colitis mice were treated with curcumin; IL-33 and IL-10 were significantly upregulated." (PMID 34567209, 2021). "IL-10 expression-inducing probiotics alleviates high-fat diet-induced obesity with colitis in mice." (PMID 34667205, 2021). "However, after treatment with L.p R3 or/and MSLZ, the anti-inflammatory factor IL-10 levels were increased and the value of IL-10/IL-17A ratio was significantly increased (p < 0.05) in the DSS-induced colitis mice." (PMID 34407839, 2021). "Il10−/−Il33−/− and Il10−/−Il33+/+ littermates developed colitis of similar severity." (PMID 33953267, 2021). "Studies in murine and porcine models of colitis have found significantly reduced disease activities after oral supplementation with indole-3-propionate or L-tryptophan by activating anti-inflammatory pathways mediated by IL-10 and IL-2242,44." (PMID 33911166, 2021). "It has been indicated that IL-10-deficient mice with high-dose T. muris infection had increased severity of colitis and heavy worm burden, implying IL-10 contributes to the development of Th2 immune response as well as regulation of IFN-γ-induced inflammations." (PMID 34451389, 2021). "To determine whether IL-10 is required for induction of IL-33 during colitis, we exposed Il10−/− mice to DSS." (PMID 33953267, 2021).
colitis (continued). "It has been reported that the anti-inflammatory cytokine IL-10 may repress colitis inflammation in patients with UC." (PMID 34835369, 2021). "Moreover, CD1d expression on B cells was found to be essential for IL-10-dependent suppression of colitis." (PMID 33995344, 2021). "Engineered Lactococcus lactis was designed to secrete IL-10 or IL-27 and attenuate colitis." (PMID 34579027, 2021). "diminuta+DNBS-treated mice produced substantial amounts of il-10, suggesting that lack of inhibition of colitis in the antibiotic-treated mice was linked to the microbiota and not a bystander effect on the host immune response to H. diminuta-infection." (PMID 34517928, 2021). "We sought to determine what molecular differences between DSS and Il10−/− colitis could lead to this difference in Il33 induction." (PMID 33953267, 2021). "Meanwhile, a previous reported oral 0.2 ml/day of A. muciniphila (3 × 109 CFU) could alleviate DSS-induced colitis mice by enhancing the mRNA expression of IL-10." (PMID 34867926, 2021). "JUG reversed the DSS-induced up-regulation of proinflammatory cytokines, including interleukin (IL)-6, 12, 21, and 23, and tumor necrosis factor-alpha, and anti-inflammatory cytokines, such as IL-10 and transforming growth factor-beta, in the serum of the colitis mice." (PMID 34421890, 2021). "However, SCFA has also been reported to skew T cells towards anti-inflammatory IL-10 production and play a role in preventing colitis and other inflammatory conditions." (PMID 34158595, 2021). "Alistipes evokes colitis and proximal colon cancers in IL10-/- mice." (PMID 34595105, 2021). "In Il10–/– mice models, Alistipes have been shown to induce colitis and tumours." (PMID 33602895, 2021). "The loss of NOD2 in IL-10-deficient macrophages reduced the production of IL-6, TNF and IL-12p40 in response to bacterial stimulation and thus dampened the usual hyper-responsiveness in the colitis mice." (PMID 34768828, 2021). "In addition, we found that curcumin promoted the release of the anti-inflammatory cytokines IL-10 and IL-33 in colitis mice and inhibited the secretion of the proinflammatory cytokines CCL-2, IL-1β, and IL-6." (PMID 34567209, 2021). "Indeed, LAG3, CD49b, CCR5, and PD1 are co-expressed on Tr1-cells in a mouse colitis model (see section Murine Tr1-cells), and in a relevant fraction of human Tr1-cells identified according to IL-10 secretion following overnight stimulation with super-Ags." (PMID 34910301, 2021). "Furthermore, proteasome inhibition was shown to decrease NFκB and TNF-α activation in the colonic tissue in the IL10−/− mouse colitis model." (PMID 34356615, 2021). "Notably, in experimentally-induced colitis murine models, F. prautznitzi can upregulate regulatory T-cells and induce IL-10 release." (PMID 34205818, 2021). "Furthermore, mice that develop spontaneous colitis due to defects in IL-2, IL-10, or TGFβ have many effector and memory T cells with TCRs that in wild-type mice are found on colonic FOXP3+ cells." (PMID 34421921, 2021). "In addition, the symptoms of rectocele and watery stools in H. hepaticus group gradually worsened compared with ΔCdtB H. hepaticus group, suggesting that CdtB is an important virulence factor of H. hepaticus induced colitis in Il-10−/− mice." (PMID 33777833, 2021). "Previous studies have shown that NAM prompts TNF-α production and reduces IL-10 levels in colitis." (PMID 33748287, 2021). "In acute colitis, we also demonstrate that L. reuteri can promote IL‐10 and suppress inflammation." (PMID 33463911, 2021). "However, treatment with C29, DW2009, or donepezil reduced LPS-induced colon shortening, myeloperoxidase activity, and TNF-α and IL-1β expression and increased IL-10 expression in the colon, leading to in the alleviation of colitis." (PMID 34579150, 2021). "Il33-expressing fibroblasts are not induced during spontaneous chronic colitis in Il10−/− mice and IL-33 deficiency does not affect colitis development or severity in Il10−/− mice." (PMID 33953267, 2021).